LGALS3 (galectin 3)
Diseases named in the same sentence as LGALS3 in open-access papers (continued):
Sharing a sentence is not in itself a finding about the gene and the disease.
melanoma (continued). "The findings that follow support the impact of ARSB and chondroitin 4-sulfation on galectin-3, c-Jun, HDAC3, and H3 on the regulation of PD-L1 expression in melanoma and suggest that ARSB may help with checkpoint inhibition." (PMID 38892038, 2024). "These discoveries led us to speculate that galectin-3 may be the unidentified natural binding ligand of MCAM in MCAM activation and MCAM-mediated melanoma progression." (PMID 36291660, 2022). "Similarly, EVs derived from the PDAC and melanoma cell lines included proteins (e.g., ALCAM and galectin-3, respectively) previously reported to be up-regulated in the serum of patients with PDAC and melanoma, respectively." (PMID 32886718, 2020). "Previous studies using intravenous injection of B16F1 melanoma cells in Lgals3−/− mice, have demonstrated an attenuation of metastatic spread in lung of these mice compared with those without deletion of galectin-3." (PMID 27526676, 2016). "A murine melanoma cell line (Tm1) that lacks galectin-3 was modified to express it or not (Tm1.G2 and Tm1.N3, respectively)." (PMID 25221735, 2014). "The evaluation of how the lack of galectin-3 in melanoma cells impairs tumor growth was done by injecting Tm1 cells subcutaneously into both WT and galectin-3 KO C57Bl/6 mice." (PMID 24421272, 2014). "Increased levels of galectin-3 were detected in the sera of patients with various cancer such as colon, melanoma, bladder, thyroid, breast, and others, however until now no one measure its level in PCa." (PMID 23625538, 2013). "Decline in ARSB leads to reduced binding of galectin-3 with C4S and increased availability of galectin-3 for nuclear translocation and cooperation with AP-1 and Sp1 in promoter activation, for expression of genes such as Wnt9A in colonic epithelium, versican in prostate cells, and CSPG4 in melanoma." (PMID 36361933, 2022). "Besides, in vitro results also demonstrated that, even without any specific stimulus, galectin-3-expressing melanoma cells secrete larger amounts of VEGF than its galectin-3 null parental cells." (PMID 24982845, 2014). "Interestingly, the absence of galectin-3 per se, either in melanoma cells or in the tumor stroma of galectin-3 KO mice, reduced tumor-associated angiogenesis." (PMID 24982845, 2014). "It is still not clear how galectin-3 expression is controlled in melanomas, obviously, it is possible that hypermethylation of its promoter may play a role in this process, though." (PMID 24421272, 2014). "Moreover, in melanoma the PAF-R antagonist reduced the proportion of COX-2-expressing cells, the microvascular density, and the proportion of activated macrophages/dendritic cells expressing galectin-3 within the tumour microenvironment." (PMID 20465821, 2010). "In addition, before exogenous contrast agents are studied in humans, a unique target protein present on melanoma cells and absent on healthy cells will need to be identified, such as galectin-3 or collagen XVII, which have recently been shown to be overexpressed in melanoma cells." (PMID 38223680, 2024).
Obesity (106 papers, 2010 to 2025). Accumulation of substantial excess body fat. "Simultaneously, prior clinical studies had proven our results that higher galectin-3 concentrations are associated with the development of obesity and type 2 diabetes." (PMID 34096884, 2021). "Mac2 (also known as Galectin-3) is a cell surface lectin receptor present on monocytes and macrophages and is released following cellular activation, and elevated levels of adipose tissue and serum galectin-3 are associated with obesity and NASH." (PMID 33378413, 2020). "Galectin-3 is well-known to stimulate differentiation and maturation of adipocytes and is associated with obesity in humans and mouse models." (PMID 32731422, 2020). "Galectin-3 is considered to be a marker of fibrosis and remodeling and associated with obesity, inflammation, T2DM and circulating levels of Galectin-3." (PMID 31890043, 2019). "Obesity and T2D are associated with galectin-3 (Gal-3) upregulation which is known to mediate inflammation and clearance of glucose adducts." (PMID 30233418, 2018). "Recently, galectin-3 has been implicated also in the development of metabolic disorders, such as obesity and type 2 diabetes, though data are still fragmentary." (PMID 26770660, 2016). "Obesity induced by accelerated high fat diet in galectin-3-deficient mice was associated with systemic inflammation." (PMID 25302080, 2014). "Obesity and type 2 diabetes are associated with increased production of Galectin-3 (Gal-3), a protein that modulates inflammation and clearance of glucose adducts." (PMID 23451284, 2013). "Here, we seek to assess the association profiles of galectin-1 and galectin-3 to glucose homeostasis and different obesity-related variables in the cross-sectional, population-based Prospective investigation of Obesity, Energy and Metabolism (POEM) cohort study from Sweden." (PMID 38777863, 2024). "Lgals3 has also been implicated in regulation of energy balance status and development of obesity." (PMID 29716523, 2018). "Recently, galectin-3 has been implicated in the development of type 2 diabetes and obesity." (PMID 26770660, 2016). "Increased levels of interleukin (IL)-6 and reduced levels of IL-10 in the sera of obese galectin-3-deficient mice might contribute to amplified obesity-induced inflammation." (PMID 25302080, 2014). "As obese children and adolescents have an increased risk of developing adult obesity and are more likely to experience significant short- and long-term health problems, it is relevant to explore potential relationships between galectin-3 versus body fat and other markers for health at a young age." (PMID 29327139, 2018). "In our study, plasma galectin-3 levels were elevated in patients with severe obesity compared to controls but showed an unexpected inverse correlation with liver fibrosis scores, contrasting with its established pro-fibrotic role." (PMID 40943431, 2025). "Key organokines such as fibroblast growth factors FGF19 and FGF21, adiponectin, galectin-3, irisin, and leptin represent well-characterized mediators of inter-organ communication with direct implications in obesity-related metabolic dysfunction." (PMID 40943431, 2025). "Markers such as sST2 and galectin-3 capture mechano-inflammatory and profibrotic signaling and retain prognostic value even when natriuretic peptide levels are confounded by age/obesity; however, they primarily reflect downstream tissue response." (PMID 41143172, 2025). "Galectin-3 null mice are protected from obesity in a dietary model, and higher galectin-3 levels in the obese appear to contribute to metabolic disease." (PMID 40649879, 2025). "In exocrine pancreas of obese organ donors, E-cadherin+ Chromogranin− epithelium showed higher expression of the pro-inflammatory adhesion molecule Galectin-3 (Gal-3), which is known to be upregulated in obesity, chronic pancreatitis and pancreatic cancer." (PMID 40909804, 2025).
Obesity (continued). "Nevertheless, a dose-dependent role for galectin-3 in obesity was supported in galectin-3 null mice that were fed a high-fat diet for a prolonged time (6 months) to become more obese, developing excess metabolic disease compared to controls." (PMID 40649879, 2025). "Chemokines, such as the monocyte chemoattractant protein 1 (MCP‐1, encoded by Ccl2), play crucial roles in recruiting circulating monocytes (Lgals3, Galectin 3+) into AT in the presence of obesity." (PMID 40847538, 2025). "In our study cohort, we found that plasma levels of galectin-3 were positively correlated with BMI and were significantly higher in patients with severe obesity compared to controls." (PMID 40943431, 2025). "We confirmed galectin-3 expression in hepatic macrophages, supporting its involvement in obesity-related metabolic inflammation." (PMID 40943431, 2025). "There was a clear distinction between the two galectins when comparing the association profiles and the Imiomics analysis for galectin-1 and galectin-3 on measures of obesity and adipose tissue distribution." (PMID 38777863, 2024). "Adipocyte differentiation and proliferation are regulated by a series of factors or molecules, among which galectin-3 (Gal-3) stimulates adipocyte differentiation and proliferation and is positively correlated with obesity." (PMID 38957396, 2024). "The association profiles for galectin-1 and galectin-3 indicate overlapping metabolic effects in humans, while the distinctly different associations seen with fat mass, fat distribution, and adipose tissue differentiation markers may suggest a functional role of galectin-1 in obesity." (PMID 38777863, 2024). "The blockage of upregulated galectin-3 was found to decrease cardiovascular fibrosis and inflammation in a diet-induced obesity animal model." (PMID 36362577, 2022). "The closely related gene Lgals3 has already been shown to protect from HFD-induced obesity in mice, but functional evidence for Lgals2 in context with T2D development is still missing." (PMID 33880624, 2021). "With raising galectin-3 levels individuals were older and more often female, and also higher prevalence of arterial hypertension, dyslipidaemia, obesity and all assessed comorbidities was present." (PMID 34561496, 2021). "In our studies, significantly higher levels of galectin 3 were found in patients with obesity and type 2 diabetes." (PMID 32859099, 2020). "To study the effect of galectin 3 expression on β cells on their function in obesity and type-2 diabetes, we combined in vivo and in vitro approaches." (PMID 32117058, 2020). "To clarify the role of galectin 3 expression in β cells during obesity-induced diabetogenesis, we used transgenic mice selectively overexpressing galectin 3 in β cells." (PMID 32117058, 2020). "Galectin-3 serum concentration positively correlates with parameters characterizing obesity and dilatation of the atria." (PMID 32784491, 2020). "Enhanced β-cell damage in obesity was correlated with an increased percentage of inflammatory macrophages expressing galectin 3 and TLR4 in the islets of TG mice." (PMID 32117058, 2020). "These in vitro findings provide a support for the clinical testing of galectin-3 inhibitors for the treatment of obesity or related diseases." (PMID 32731422, 2020). "Since the Teklad 7012 diet is 17% fat, and mouse dietary requirements are estimated at 5% fat, it is reasonable to suggest that the increase in Lgals3−/− body weight/adiposity we observe in part replicates prior findings of high-fat-diet-induced obesity." (PMID 29716523, 2018). "Galectin-3 is expressed in many tissues, including the heart, and its circulating levels significantly increase in obesity." (PMID 30231508, 2018). "In adults, galectin-3 has been shown to be elevated in obesity, and we confirm a relation to body fat measurements in an unselected population of children." (PMID 29327139, 2018).
Obesity (continued). "Galectin-3 (Gal-3) is a member of a β-galactoside-binding lectin family produced in the heart and whose expression is upregulated in obesity." (PMID 29361517, 2018). "Altogether, these data indicate that galectin-3 deserves further attention in order to clarify its role as a potential player and therapeutic target in obesity and type 2 diabetes." (PMID 26770660, 2016). "Several experimental studies have investigated the role of galectin-3 in the development of type 2 diabetes and obesity." (PMID 26770660, 2016). "In type 2 diabetes, it was reported that systemic galectin-3 is elevated in obesity and is negatively correlated with glycated hemoglobin." (PMID 25302080, 2014). "The molecular players that link IBD and obesity have yet to be identified, but as outlined in more detail below, the roles for galectin-3 in intestinal epithelium and adipose tissue may provide functional connectivity between these tissues." (PMID 40649879, 2025). "Galectin-3 is expressed by various human cells, especially immune cells, adipocytes, epithelial cells, and endothelial cells, and serum galectin-3 levels are elevated in obesity." (PMID 38731984, 2024). "Long-term (20-week) HFD-induced obesity led to interstitial accumulation of the lectin family protein galectin-3 (Gal-3), a potent chemoattractant involved in cell adhesion, cell cycle progression, apoptosis, inflammation, cell proliferation, and differentiation." (PMID 38788527, 2024). "Additionally, both galectin-1 and galectin-3 were associated with IL-10 and TNF signaling, pathways previously related to galectins and with a role in obesity-related inflammation and lipid metabolism." (PMID 38777863, 2024). "Moreover, circulating galectin-3 levels were found to be higher in the obese, and were associated with metabolic diseases, implying a potential link between galectin-3 levels in virus-related infections and inflammatory events in obesity." (PMID 37238973, 2023). "Adipocytes also express galectin-3, and circulating levels of galectin-3 are increased in obesity." (PMID 37189804, 2023). "How do LPA and galectin 3 coordinate the activation of this pathway in obesity?" (PMID 34957117, 2021). "Apart from the higher galectin-3 levels in EC patients compared to normal endometrium, significantly higher values of galectin-3 levels were found in patients with obesity, type 2 diabetes and increased levels of C-reactive protein and in nulliparous vs. multiparous women." (PMID 33799622, 2021). "In galectin-3 knockout mice, a high-fat diet did not cause fat cell hypertrophy, suggesting that galectin-3 was involved in the pathogenesis of obesity." (PMID 35141299, 2021). "According to the most recent reports, galectin 3 may be involved in the development of obesity and type 2 diabetes." (PMID 32859099, 2020). "According to the correlation analysis, galectin-3 relationship with anthropometric parameters characterizing obesity was identified in the general sample of the examined: body mass index (BMI; r = 0.352, p < 0.0001) and waist circumference (r = 0.362, p < 0.0001)." (PMID 32784491, 2020). "During obesity, hematopoietic cell-derived galectin 3 induces insulin resistance." (PMID 32117058, 2020). "In adults, galectin-3 has been shown to be elevated in obesity." (PMID 29327139, 2018). "Hepatic galectin-3 is induced in obesity, and systemic galectin-3 is increased." (PMID 28661458, 2017). "Recent evidence suggests that galectin-3 may also participate in the development of obesity and type 2 diabetes." (PMID 26770660, 2016). "Galectin-3, another notable protein within the context of the adipose tissue secretome and autophagy, has been identified as a biomarker for metabolic syndrome and obesity, attributed to its elevated levels in the plasma of patients with obesity and type 2 diabetes." (PMID 39118171, 2024).
Obesity (continued). "In agreement, Grewal and Buechler demonstrated that adipokines, mainly leptin, resistin and galectin-3, are closely involved in peripheral monocytes and neutrophil responses, which contributes to complications during the course of COVID-19 in patients with obesity." (PMID 37626613, 2023). "However, further studies and clinical trials should be performed comprising the cellular and molecular states to clarify the exact mechanism of Galectin-3, TGF-β, and PAI-1 and also their effects on the association of obesity with mood disorders through following LCD." (PMID 34516574, 2021). "Moreover, young (12-week-old) galectin-3 deficient mice fed a standard diet exhibited altered glucose homeostasis in the absence of obesity and associated abnormalities." (PMID 25302080, 2014). "We also found that diet-induced obesity increased the secretion of tumor necrosis factor-α (TNF-α), interleukin-6 (IL-6), and galectin-3." (PMID 40565066, 2025). "However, further studies are required to determine 1) how galectin-3 regulates follicular growth and ovarian function; 2) if, and how, obesity alters galectin-3 in PCOS subjects; and 3) whether and how metformin could reduce the galectin-3 levels in PCOS subjects." (PMID 37033997, 2023). "Among many genes which have been analyzed to understand obesity and related metabolic traits among children and adolescents, not many studies are conducted on LGALS3 gene, especially in population of children." (PMID 39139163, 2024). "Here, for the first time we demonstrated that Galectin-3, TGF-β, and PAI-1 may act as a critical link between obesity and depressive symptoms, and as a consequence, they may represent a possible novel insight in the disease monitoring and treatment." (PMID 34516574, 2021). "Galectin-3 (Gal-3) induces cardiac inflammation and fibrosis in the context of obesity; however, its role in the metabolic consequences of obesity is not totally established." (PMID 29361517, 2018). "Neither sex, age, blood pressure, Killip class on admission, history ofhypertension, hyperlipidemia, renal failure, lung disease, new-onset atrialfibrillation or obesity had any effect on galectin-3 levels, neither onadmission, nor on day one or day five of hospitalization." (PMID 39077714, 2022). "Thus suggesting a direct positive modulation of beta-cell function by galectin-3 independent of obesity-related inflammation." (PMID 25302080, 2014). "However, we believe that galectin 3 and LPA may also promote the expression of CD36 in NPC hepatocytes through the PPAR-γ pathway, contributing to lysosome dysfunction probably by analogous mechanisms observed in obesity." (PMID 34957117, 2021).